BNC2 (basonuclin zinc finger protein 2)
Diseases named in the same sentence as BNC2 in open-access papers (continued):
Sharing a sentence is not in itself a finding about the gene and the disease.
liver cancer (1 paper, 2016). An epithelial or non-epithelial malignant neoplasm that arises from the liver. "Unlike BNC1, the promoter region of BNC2 was seldom hypermethylated in both liver cancer cell lines and HCC tissues." (PMID 26821013, 2016). "In line with the results in liver cancer cell lines, no methylation of the BNC2 gene was identified in HCC tumor tissues." (PMID 26821013, 2016).
lung carcinoma (1 paper, 2017). "In this study, the mRNA expression of BNC2 was analyzed in lung squamous cell carcinoma tissue samples and a lung cancer cell line." (PMID 28184177, 2017). "Our results suggest that BNC2 is a tumor suppressor gene with reduced expression in lung cancer cells and with the capacity to inhibit cell proliferation and to up-regulate IFN-regulated genes." (PMID 28184177, 2017). "BNC2 expression was studied in the A549 and BEAS-2B cell lines, as well as in lung cancer tissue." (PMID 28184177, 2017). "We showed the reduced mRNA expression of BNC2 in non-small cell lung cancer tissue and lung cancer cell line A549 compared to non-cancerous lung tissue and BEAS-2B cells, respectively." (PMID 28184177, 2017). "The role and expression of the BNC2 gene in lung cancer has not yet been investigated." (PMID 28184177, 2017).
lymph node metastasis (1 paper, 2022). "In OC tissues, the low expression of circ-BNC2 was associated with the advanced Federation International of Gynecology and Obstetr (FIGO) stage and positive lymph node metastasis of the patients." (PMID 35965327, 2022).
schizophrenia (1 paper, 2020). A major psychotic disorder characterized by abnormalities in the perception or expression of reality. "BNC2 is another gene thought to play a role in human skin color determination, whereas the gene APOL4 is significantly up-regulated in people diagnosed with schizophrenia." (PMID 32853200, 2020).
type 1 diabetes (1 paper, 2011). "In addition to a strong association with HbA1c, the BNC2 and SORCS1 risk alleles have revealed associations with mean glucose levels in type 1 diabetes, suggesting that these genetic variations affect HbA1c through their effects on glucose." (PMID 21294870, 2011).
type 2 diabetes (1 paper, 2011). "We genotyped 1,486 subjects with type 2 diabetes from a Norwegian population-based cohort (HUNT2) for single-nucleotide polymorphisms (SNPs) located near the BNC2, SORCS1, GSC and WDR72 loci." (PMID 21294870, 2011).
urofacial syndrome (1 paper, 2022). "Several monogenic causes of other congenital bladder outflow obstruction disorders have been described including BNC2 in urethral stenosis; FLNA in syndromic urethral anomalies; HPSE2 and LRIG2 in urofacial syndrome; CHRM3 in prune-belly like syndrome; and MYOCD in megabladder." (PMID 36124557, 2022).
tumor (20 papers, 2012 to 2026). "As the microenvironment is largely shaped by the actions of fibroblasts, and endogenous BNC2 is most broadly and highly expressed in fibroblasts, we sought to question in which population of tumour-associated cells that BNC2 is expressed most highly." (PMID 37536977, 2023). "Likewise, we note an intriguing paradox whereby reduced BNC2 expression is generally associated with tumours; however, very high BNC2 expression is associated with poor patient prognosis and higher tumour grade." (PMID 37536977, 2023). "Despite generally lower levels within the bulk tumour, BNC2 expression increases with cancer stage and elevated BNC2 expression correlates with lower survival." (PMID 37536977, 2023). "BNC2 is thereby identified as a novel regulator of the tumour microenvironment where its high expression correlates with poor prognosis." (PMID 37536977, 2023). "In particular, considerable data have indicated that Basonuclin 2 (BNC2), the parental gene of circ_0086414, acts as a tumor suppressor in the esophagus and its downregulation occurs in EC development." (PMID 35549806, 2022). "RT-qPCR assays showed that BNC2 expression is significantly induced in human cirrhotic livers when compared to histologically normal areas of livers from patients who underwent tumor resections." (PMID 36088459, 2022). "Circ_0086414 is located in chr:916435552-16437522 and formed by the back-splicing of BNC2, which is a highly conserved protein and is regarded as a tumor repressor in different types of cancers like bladder, esophageal and glioblastoma cancers." (PMID 35549806, 2022). "Human basonuclin 2 (BNC2) acts as a tumor suppressor in multiple cancers in an as yet unidentified manner." (PMID 28184177, 2017). "Next, we tested the expression levels of BNC1 and BNC2 in 30 pairs of matched tumor and their adjacent non-tumor tissues." (PMID 26821013, 2016). "Meanwhile, we collected at our Institute an original cohort of HGSOC and tumor-free control samples (fallopian tube and ovarian), in which we confirmed by quantitative real-time PCR (qRT-PCR) that BNC2 expression was reduced in HGSOC." (PMID 27899818, 2016). "So far, few groups have published results regarding the role of BNC2 in cancer, but all suggested a putative tumor suppressor function of BNC2,24, 25, 26 in agreement with our findings." (PMID 27899818, 2016). "Numerous lines of investigation have demonstrated that the aberrant expression of BNC1 and BNC2 contribute to tumor progression." (PMID 26821013, 2016). "Determining whether BNC2 functions as a tumour suppressor or an oncogene is therefore a nuanced question that requires further investigation, particularly in relation to the impact on cancer development from its role in matrisome-secreting fibroblasts." (PMID 37536977, 2023). "Collectively, circ-BNC2 is identified as a novel tumor suppressor in the progression of OC." (PMID 35965327, 2022). "Published data suggest that BNC2 could be an activator of a subset of interferon-regulated genes and might thereby act as a tumor suppressor gene." (PMID 35457141, 2022). "Thus, our data are in line with previous studies that report the down-regulation of the BNC2 gene in cancers of epithelial origin and indicate that BNC2 has a tumor-suppressive function." (PMID 28184177, 2017). "In addition, we also detected the methylation status of BNC2 in 16 pairs of tumor and adjacent non-tumor tissues." (PMID 26821013, 2016). "Little is known about the expression and function of BNC2 in tumor progression." (PMID 26821013, 2016). "Similarly, the tumour promoting or suppressing role of BNC2 appears to be similarly complex." (PMID 37536977, 2023).
tumor (continued). "The poor prognosis of patients expressing the highest levels of BNC2, and the elevated expression of BNC2 at more advanced cancer stages, may be more indicative of infiltrating fibroblasts than it is necessarily that of BNC2 expression in the tumour cells themselves." (PMID 37536977, 2023). "Importantly, based on our data for 7 Ba/Sq samples, we were able to identify higher enhancer activity associated with potential key genes in Basal tumour biology, including cell surface receptors (IL7R, OSMR, EGFR, MET) and transcriptional regulators (BNC2, HMGA2, KLF7, NR3C1)." (PMID 36944729, 2023). "There is a possibility that BNC2 may act as a tumour suppressor in the cancer cells in which it is expressed (decreasing motility for example), but the presence of high levels of BNC2 in tumour bulk sequencing could still be indicative of fibroblast infiltration and thus, poorer outcomes." (PMID 37536977, 2023). "We find that BNC2 is almost exclusively expressed in cancer-associated fibroblasts, especially those of the s5 myofibroblast-like subtype and was absent in the epithelial tumour cells themselves (at least in this cohort of patients)." (PMID 37536977, 2023). "Among the altered genes, BNC2 is a putative tumor suppressor; RASA1 gene (Ras p21 protein activator 1) is the regulator of Ras oncogene, and mutation in RASA1 may turn on oncogenic pathways; Smad2 is a tumor suppressor; and Yap1 is an oncogenic co-activator in the Hippo pathway when overexpressed." (PMID 36865791, 2023). "Among them, BNC2, SYNM, and TCF21 target genes were detected in all tumor locations, and three targets (GRIK2, KLHL14, and MS4A2) were shared by R-CRC and L-CRC but not by RC." (PMID 37987361, 2023). "We also identified genes encoding membrane receptors (IL7R, OSMR, EGFR) and transcriptional regulators (BNC2, BNC1, HMGA2, KLF7, NR3C1) as enriched in Basal tumours." (PMID 36944729, 2023). "In this study, the expression levels and methylation statuses of BNC1 and BNC2 were investigated in primary HCC tissues and their corresponding adjacent non-tumor liver tissues, in order to investigate the potential roles of BNC1 and BNC2 genes in HCC." (PMID 26821013, 2016). "Furthermore, we developed a prognostic nomogram based on IMPG2, BNC2, PAPPA2, ITGBL1and UNC13C expression levels in tumor cells to predict survival outcomes." (PMID 42157926, 2026). "Our data suggest that human BNC2 is an activator of a subset of IFN-regulated genes and might thereby act as a tumor suppressor." (PMID 28184177, 2017). "Next, we tested the expression of BNC2 in 8 pairs of matched SCC and adjacent non-tumor tissues." (PMID 28184177, 2017). "Thus, our results suggest that BNC2 has the capacity to increase the expression of IFN-regulated genes and thereby act as a tumor suppressor gene in lung epithelial cells." (PMID 28184177, 2017). "Taken together, these data suggest that BNC2 regulates the production and degradation of the ECM, not only within cancer cells themselves but also in cancer-associated fibroblasts that are fundamental to establishing the tumour microenvironment." (PMID 37536977, 2023). "No methylation of the BNC2 promoter was found in HCC tumor tissues." (PMID 26821013, 2016).
cancer (8 papers, 2016 to 2025). A tumor composed of atypical neoplastic, often pleomorphic cells that invade other tissues. "Here, we demonstrate that basonuclin-2 (BNC2), a mesenchymal-expressed gene, that is, strongly associated with cancer and developmental defects across genome-wide association studies, is a novel regulator of ECM composition and degradation." (PMID 37536977, 2023). "Similar studies also note the association of BNC2-related SNPs across a range of cancer types (esophageal, prostate, bladder, liver, skin, uterus, stomach, and lung)." (PMID 37536977, 2023). "In so doing, BNC2 modulates the motile and invasive properties of cancers, which likely explains the association of high BNC2 expression with increasing cancer grade and poor patient prognosis." (PMID 37536977, 2023). "Despite extensive linkage to cancer via GWAS, a role for BNC2 as a regulator of the ECM is only now emerging." (PMID 37536977, 2023). "Multiple studies have demonstrated the down-regulation of BNC2 in numerous cancers." (PMID 28184177, 2017). "Collectively, the identification of the genes with which BNC2 is co-expressed in cancer patients (“red” module), and the matrisomal genes whose expression is affected by BNC2 perturbation, indicate that BNC2 may serve as a novel regulator of ECM composition and processing." (PMID 37536977, 2023). "We hypothesise that the extensive regulation of ECM composition and digestion, that is, controlled by BNC2 in both cancer cells and fibroblasts is central to its frequently reported role in cancer and development, but which until now has remained largely mechanistically uncharacterised." (PMID 37536977, 2023). "The impact of reintroducing ZIC4 on innate immune response in our model system could also be seen with other zinc finger proteins, like BNC2 (human basonuclin 2) and ZNF395 in cancer cells." (PMID 39266576, 2024). "Many novel factors that have previously been associated with embryo development but not with cancer, such as ATOH, TSHZ, BNC2 and OLIG, were identified in this study." (PMID 28821798, 2017). "As these data were obtained from the bulk sequencing of tissue, and because BNC2 is most highly expressed in fibroblasts, one explanation is that the prognostic impact of BNC2 does not derive from BNC2 expressed in the cancer cells themselves, but as a marker of infiltrating fibroblasts." (PMID 37536977, 2023). "We find BNC2 is not simply another general promoter of the mesenchymal phenotype, but instead regulates the composition and digestion of the ECM, which is consistent with the migratory, invasive phenotype that endogenous BNC2 promotes in cancer cells." (PMID 37536977, 2023).
digestive system cancer (1 paper, 2025). A primary or metastatic malignant neoplasm involving any part of the digestive system. "After comparing the co-expressed genes in these five digestive system cancers, five genes, PKD2, CDH11, OSMR, ITGB1, and BNC2, were further identified as being associated and interacting with ITGAV through the Venn diagram." (PMID 40018050, 2025).
BNC2 also shares sentences with these, for which no sentence is quoted: infection (3 papers); cleft palate (2); congenital lower urinary tract obstruction (2); cryptorchidism (2); gastric cancer (2); idiopathic scoliosis (2); marginal zone lymphoma (2); Micropenis (2); bacterial infection (1); bladder-exstrophy-epispadias complex (1); Candidemia (1); ciliopathies (1); cleft lip (1); COVID-19 (1); cystic kidney disease (1); disseminated candidiasis (1); exstrophy-epispadias complex (1); fibrosis (1); frontometaphyseal dysplasia (1); glioma (1); Hermansky-Pudlak syndrome (1); Infertility (1); keloid (1); malaria (1); metabolic disorders (1); neuropathies (1); orofacial clefting (1); ovarian serous cystadenocarcinoma (1); PNS neoplasms (1); prostate tumours (1).
A further 6 diseases each share a sentence with BNC2 in 1 paper.